MSLN (mesothelin)
Diseases named in the same sentence as MSLN in open-access papers (continued):
Sharing a sentence is not in itself a finding about the gene and the disease.
tumor (continued). "Interestingly, the level of MSLN expression was positively correlated with the distance of the primary tumor from the liver." (PMID 41400642, 2025). "Anti-MSLN CARs facilitated paclitaxel delivery and cytotoxic granules to tumor cells, while anti-PD-L1 CARs efficiently reversed the immunosuppressive effect of the tumor microenvironment." (PMID 41511353, 2025). "Pretreatment with folate receptor beta-specific CAR-T cells prior to anti-mesothelin CAR-T cell therapy can modulate the tumor immune microenvironment and improve the effectiveness of anti-mesothelin CAR-T cells, which is conducive to better therapeutic effects." (PMID 39253578, 2024). "When the tumor volume reached 100 mm3, the mice were categorized into different treatment groups, each receiving one among cGAMP, NK-92 cells, cGAMP along with NK-92 cells and anti-MSLN CAR-NK-92 cells in combination with cGAMP (combination group)." (PMID 38694508, 2024). "The anti-FAP CAR-T cells effectively eliminated stromal cells and depleted the immunosuppressive matrix, and subsequent treatment with anti-MSLN CAR-T cells led to improved tumor control, suggesting that stromal depletion sensitized the tumor to treatment with the anti-MSLN CAR-T cells." (PMID 39796666, 2024). "Thus, MSLN-NK cells derived from iPSCs can effectively kill MSLN-positive TNBC tumor cells in vitro and in vivo." (PMID 38694508, 2024). "MSLN plays a key role in promoting migration and invasion of tumor cells through EMT." (PMID 38628720, 2024). "Taken together, last decades' radiopharmaceuticals have been primarily targeting tumor cell membrane proteins (B7-H3, CXCR4, FRα, HER2, integrin αVβ3, L1CAM, mesothelin, MISRII and NaPi2b) besides the (intra-)nuclear target PARP-1 and the FAP-associated tumor microenvironment." (PMID 39431018, 2024). "Firstly, using the relevant data of IHC in the HPA database, the key genes CDKN2A, MSLN, and CKMT2 were compared at the protein level, and it was found that CDKN2A and MSLN were significantly highly expressed in the tumor tissues (p < 0.001; p < 0.05), which was consistent with our prediction." (PMID 39519383, 2024). "Also, the vaccine recruits DCs that cross-prime and generate MSLN-specific CD8+ T cells, which are capable of destroying tumor cells expressing MSLN." (PMID 38835055, 2024). "Additionally, all VHH CAR variants with alanine substitutions maintained cross-reactivity with mouse MSLN, allowing the assessment of on-target, off-tumor toxicity in mouse models." (PMID 39576012, 2024). "Our work begins to uncover the relevance of MSLN overexpression in CRC patients as well as the implications of MSLN expression levels on pivotal CRC prognostic information, including CRC tumor sidedness, CMS subtype, genetic mutation landscape, and immune response modulation." (PMID 39174744, 2024). "However, fatal off-tumor toxicity of high-affinity MSLN-targeting CAR T cells has been reported in multiple clinical trials." (PMID 39576012, 2024). "Previous studies have shown that MSLN may play a role in regulating tumor cell proliferation, apoptosis, adhesion, invasion, metastasis, and chemotherapy resistance." (PMID 39023820, 2024). "Similarly, 24-h exposure to treosulfan or fludarabine (10 μM) did not impact MSLN-CAR T cells CD107a expression, cytokine production, or tumor killing when co-incubated with MSLN+ target T cells in normoxia or hypoxia." (PMID 38954005, 2024). "Some studies have concluded that MSLN plays an important role in tumor migration and invasion." (PMID 38570866, 2024). "ZipFV’s scFvs were developed to specifically target the tumour antigens Her2, Axl, and mesothelin." (PMID 39596267, 2024). "We interpret these results to indicate that CAR T cells prepared with a ligand-binding domain of MUC16 based on mesothelin may potentially evade host immune responses to scFv and maintain anti-tumor activity." (PMID 38637885, 2024).
tumor (continued). "Among these, EGFR and MSLN seem to be the more promising targets compared to others: indeed, they showed higher antigen specificity and lower on-target, off-tumor toxicity concern, i.e., the potential healthy organ toxicity, due to the expression of these targets in tissues other than tumor." (PMID 39199653, 2024). "Also, 2 Gy x 2 fractions combined with anti-mesothelin CAR-T cells also significantly improved tumor control and survival (Figure 3F2) relative to LDRT alone [p<0.0001]) and CAR-T therapy alone (p<0.0001)." (PMID 39445067, 2024). "Mesothelin may be crucial for tumor implantation and metastasis, although its typical physiologic function is yet to be well understood." (PMID 39456611, 2024). "Because the expression of matrix metalloproteinase family members (MMPs) is essential for tumor progression and metastasis, we further analyzed whether MMPs are involved in the MSLN-induced enhanced aggression of brain metastatic cells." (PMID 38570866, 2024). "The binding of CAR-T cells may be limited in space; furthermore, the potency of CAR-T cells may be weakened or lost due to binding with shed MSLN before they reach the tumor cells or release from the cell surface along with shed MSLN." (PMID 39023820, 2024). "When anti-MSLN CAR-T cells combined with OAd-TNFa-IL2 (an oncolytic adenovirus expressing TNF-α and IL-2) were applied to human PDA xenotransplantation mice, the activity, proliferation, tumor invasion and killing ability of the resulting anti-MSLN CAR-T cells were enhanced." (PMID 39023820, 2024). "When compared to normal tissues, mesothelin expression was increased in most tumours." (PMID 39548594, 2024). "While targeting tumor cells, anti-MSLN CAR-T cells may also kill normal tissue cells expressing MSLN, resulting in off-target effects." (PMID 36900151, 2023). "Of note, in the control group high frequency of MSLN+ tumor cells was detected at the intermediate time point and lower at the humane endpoint, while the frequency of MSLN+ tumor cells in MSLN-CAR-treated mice was low at both the intermediate and humane endpoint." (PMID 36746513, 2023). "None of the tumour characteristics (e.g. histology) were significantly associated with MSLN expression." (PMID 37047331, 2023). "The 3.7-fold higher uptake of [68Ga]Ga-NODAGA-S1 in MSLNhigh A1847 than in MSLNlow MDA-MB-231 tumours associated with the competing effect of non-labelled S1 and a low off-target uptake confirmed the specific targeting of MSLN by Nb S1." (PMID 37388728, 2023). "We immunohistochemically stained the tumour samples against MSLN and CXCR4." (PMID 37047331, 2023). "Impressively, LCAR-M23 T cells efficiently eradicated tumours in all 6 MSLN-positive PDX models." (PMID 36166071, 2023). "After CAR T cell therapy, MSLN expression in tumor cells decreased progressively." (PMID 37274261, 2023). "Furthermore, adding PH20—a human hyaluronidase that controls tumor progression—enhanced mesothelin-CAR T cell activity against GC." (PMID 38067366, 2023). "Tumor cell MSLN expression was examined in epithelioid and sarcomatoid MESO histotypes, which showed that high expression of MSLN was significantly associated with MESO epithelioid cells, whereas low expression of MSLN was detected in sarcomatoid cells (P < 0.001)." (PMID 37901248, 2023). "In contrast to these data, a large single‐centre analysis of stage III epithelioid tumours found that T3 tumours had a greater percentage of strong MSLN immunostaining compared to T2 tumours (51 versus 25%), suggesting that invasiveness was associated with increased MSLN expression." (PMID 37040900, 2023). "The study found that Anetumab ravtansine demonstrated potent anti-tumor activity in vitro and in vivo, selectively targeting and killing mesothelin-expressing tumor cells through a bystander effect, which involves the transfer of the drug to neighboring cells that do not express the target protein." (PMID 37298631, 2023).
tumor (continued). "Fourth-generation anti-MSLN-CAR-T cells induced significant T cell infiltration which, in turn, caused the regression of pre-established solid tumors and extended survival in a mouse tumor xenograft model." (PMID 37457288, 2023). "In another study, the intravenous injection of interleukin 7 (IL-7) and Chemokine (C-C motif) ligand-19 (CCL19)-MSLN secreting CAR-T cells (NCT03198546) in a patient with advanced pancreatic cancer induced complete regression of the tumor 240 days post-treatment." (PMID 36717905, 2023). "Together, these findings indicated that CAR-Exos may target tumor cells through the interaction between the anti-MSLN scFv on the surface and the MSLN on LLC cells." (PMID 37308954, 2023). "Through a collective analysis encompassing molecular docking insights, immunoprecipitation data, and RNA silencing experiments, it became evident that MSLN, a recognized tumor differentiation antigen, played a significant role in mediating the anti-tumor effects of PSCA." (PMID 37894284, 2023). "Notably, LCAR-M23 CAR T cells efficiently eradicated tumours or inhibited tumour growth in all 6 MSLN-positive PDX models." (PMID 36166071, 2023). "However, mesothelin overexpression occurs in approximately 30% of human cancers, which makes it an attractive tumor antigen for targeted cancer therapy, including T-cell-based treatments." (PMID 37501016, 2023). "A biopsy taken on day +365 at time of tumor progression showed high mesothelin expression, suggesting that antigen loss was not a reason for the progression of her tumor." (PMID 37501016, 2023). "In vitro tumor killing capacity was enhanced in ACOD1-/- MSLN-CAR-iMACs which could be reversed by supplementing 4-OI." (PMID 37723178, 2023). "After inhalation, the main biodistribution of PTX@CAR-Exos was observed to be the lungs, and the exosomes expressing anti-MSLN scFv as a vehicle exhibited some ability to target tumor cells, resulting in an accumulation of the drug in the tumor and increasing its efficacy." (PMID 37308954, 2023). "In this study, we found that MSLN was expressed in >64% of MPM tumor specimens (49% showing high expression), suggesting that high MSLN expression may predict the response to treatment and patient outcomes." (PMID 37901248, 2023). "Fourteen patients with mesothelin-expressing tumours were treated in this clinical study." (PMID 36829563, 2023). "Similar results were obtained in another phase I study in fifteen enrolled adult patients with measurable MSLN+ (≥10% of tumor cells expressing MSLN) locally advanced or metastatic solid tumors who failed at least one standard therapy or were unable to tolerate chemotherapy." (PMID 37296972, 2023). "MSLN can promote tumor proliferation, metastasis, and resistance to chemotherapy." (PMID 37359558, 2023). "Overall, 62 tumours (59.0%) showed MSLN protein immunohistochemical expression." (PMID 37047331, 2023). "Taken together, these data suggest that the reduced CIM, CD56 and MSLN expression levels by M1xx CAR T cells could be explained by the rapid M1xx-mediated clearance of tumor cells in vivo." (PMID 36746513, 2023). "All anti-MSLN PET agents demonstrated significantlyhigher tumor uptake (p ≤ 0.05) at 18, 48,and 96 h as compared to the negative control [89Zr]Zr-VH-Fc Ab6, while only the anti-MSLN VH-Fcs PET agents (2A10, 3C9)demonstrated significantly higher tumor uptake at 144 h (p ≤ 0.01)." (PMID 38027361, 2023). "Target antigens could include: A) tumor associated cell surface antigens (PD-L1, CD20, CD19, MSLN (Mesothelin), Claudin18.2, and Her2), B) immune checkpoint proteins (PD-1, CD40, 41BB), and C) cytokines or receptors (CSF-2 receptor, VEGF)." (PMID 35418166, 2022). "MSLN expression was observed in 98.4% (121/123) of primary tumours." (PMID 36434635, 2022). "Thus, a CAR T cell strategy against CA125 and MSLN would target most tumour cells in the majority of cases." (PMID 35565412, 2022).
tumor (continued). "This work, together with our recent reported PDL1-Vax, lays out a new strategy to overcome the problem of immune tolerance, and promotes the development of drugs targeting MSLN as the relevant antigen, which have theoretical and application values in the development of tumor immunotherapy in human." (PMID 35795680, 2022). "Since mesothelin is a membrane antigen that is overexpressed in a variety of solid neoplasms, including HSOC, there are many studies in the literature that have proven that radio immunoimaging analysis can be used for the non-invasive detection of MSLN-overexpressing tumours." (PMID 35565412, 2022). "We also observed that MSLN was a good prognostic biomarker, and its expression was positively correlated with tumor-infiltrating monocytes, which may possess the role of MSLN-specific CAR monocytes in LUSC." (PMID 35993054, 2022). "Shed mesothelin could decrease the efficacy of targeted therapies, resulting in an on-target, off-tumor response of the drugs interacting with soluble mesothelin." (PMID 35326701, 2022). "Human anti-FAB or anti-mesothelin CAR T cells intravenously injected into immunodeficient mice bearing subcutaneous mesothelin-positive tumors and then isolated from these tumors showed a loss of functionality limiting their anti-tumor cytotoxicity." (PMID 35203517, 2022). "Moreover, in PTT, expression of CA125 and MSLN appeared to be mostly restricted to tumor cells at the margin of the stroma, which are less detectable within PDM." (PMID 35740561, 2022). "This outcome could be explained by low expression of mesothelin on tumor cells, that would limit bsAb accessibility to the tumor and thus its ability to crosslink the CD40 receptor, which is required for CD40 signaling." (PMID 35911742, 2022). "The results indicated that the upregulated hub genes COL7A1 and JUP were negatively correlated with tumor-infiltrating monocytes, while the downregulated hub genes MSLN and CHRDL1 were positively correlated with tumor-infiltrating monocytes, with a p value < 0.05." (PMID 35993054, 2022). "High MSLN expression was defined as an intensity of ≥ 2 + in ≥ 30% of tumour cells." (PMID 36434635, 2022). "Our results indicate that MSLN is closely related to immune cell infiltration, which may affect the activation of the tumor immune response that regulates the tumor progression." (PMID 35692779, 2022). "Mesothelin is a tumor differentiation glycoprotein involved in cell adhesion." (PMID 36483567, 2022). "IHC showed that MSLN expression was still present in the tumors of treated as well as untreated mice, consistent with the sustained upregulation of exhaustion markers we observed on tumor-infiltrating T cells." (PMID 35264436, 2022). "These MSLN-targeted therapies may improve treatment outcomes for advanced stage tumours with high MSLN expression." (PMID 36434635, 2022). "Thereby, Mesothelin (MSLN) and Mucin-16 (MUC16), also known as cancer antigen 125 (CA-125), were identified as the two top OvCa-associated antigens presented on approximately 80% and 50% of analyzed tumor samples, respectively." (PMID 35565389, 2022). "However, the ultrastructure of the mesothelial lining was affected in the MSLN knockout mice, indicating a possible role for mesothelin in shaping the tumor microenvironment." (PMID 35326701, 2022). "Furthermore, the fourth generation of anti-MSLN-CAR-T cells illustrated a dramatic antitumor capability with complete tumor regression and overall improved survival in mouse models." (PMID 35414783, 2022). "Mesothelin, however, has remained insufficient as a marker of tumor prognosis and its functions in MPM and other solid tumors remain largely unknown." (PMID 36303838, 2022). "Moreover, MSLN-CAR-T cell therapy inhibited tumor growth and metastasis in MDA-MB-231 xenograft models." (PMID 35414783, 2022).
tumor (continued). "Several circulating proteins and RNA molecules have been proposed as diagnostic and prognostic biomarkers of MPM but only the glycoprotein mesothelin has been approved by the US Food and Drug Administration as a biomarker used to determine tumor response to treatment." (PMID 36303838, 2022). "High MSLN expression was observed in 63.4% (78/123) of primary tumour samples." (PMID 36434635, 2022). "The function of mesothelin is not established but it may act as a binding site for transmembrane mesothelin and mucins expressed by tumor cells." (PMID 36497364, 2022). "In addition, overexpression of MSLN in PDAC is found in almost all tumours, which is interesting knowing the particularly high heterogeneity of these tumours." (PMID 35892707, 2022). "Which tumor entities might benefit most from anti-MSLN therapies is difficult to predict since the literature on MSLN expression is controversial for many tumor entities." (PMID 33917081, 2021). "Recent reports indicate that mesothelin may play an important role in cell adherence, cell survival/proliferation, tumor progression and chemoresistance." (PMID 33637083, 2021). "Importantly, adoptive transfer of P4 CAR-expressing T cells mediated the regression of large, established tumor in the presence of soluble mesothelin in a xenogenic model of human ovarian cancer." (PMID 34926461, 2021). "Moreover, studies have reported the various roles of MSLN in cell survival/proliferation, tumor progression, and chemoresistance." (PMID 33670777, 2021). "Subsequent studies have however identified numerous other tumor entities with MSLN expression." (PMID 33917081, 2021). "Mesothelin is widely expressed in many tumours, including 70% of ovarian cancers." (PMID 33800113, 2021). "Finally, mesothelin is involved in epithelial-mesenchymal transition, a process known to contribute to tumor invasiveness." (PMID 34522225, 2021). "The mouse treated with MSLN scFv-LGA-PEI/miR-520h mimics NPs showed stronger red fluorescence in the PAN3 tumor than that treated with the LGA-PEI/miR-520h mimics NPs did, indicating MSLN scFv-LGA-PEI can deliver more RNA into the tumor tissue with high MSLN expression than LGA-PEI does." (PMID 34577541, 2021). "In addition, MSLN-specific CAR-T cells in patients with malignant tumors have shown anti-tumor activity." (PMID 34839348, 2021). "Mesothelin is limitedly expressed on mesothelial cells in different types of tissues including pleura, peritoneum, and pericardium but is highly expressed as a tumor-differentiation antigen in a broad spectrum of solid tumors, which make mesothelin as an attractive target for cancer immunotherapy." (PMID 33968014, 2021). "Here, we found that Tandem CAR-T cells could specifically recognize either FOLR1- or MSLN-positive tumor cells and exhibited a superior antitumor effect with a lower E:T ratio than single-target CAR-T cells." (PMID 34803504, 2021). "For this, mesothelin (MSLN) is a promising candidate for tumor-specific therapy." (PMID 33670777, 2021). "The current study along with several preclinical and clinical studies demonstrate the significance of MSLN expression in both the host and tumor cells, making MSLN a promising target for OvCa treatment as current therapeutic effects seem moderate at best indicating further investigation is needed." (PMID 34830322, 2021). "Although targeting MSLN region I (like the SS1 scFv does) blocks the MSLN tumor-promoting interaction with MUC16, a preclinical study suggested that MSLN region III is a better target as it mediated a stronger activation and cytotoxicity compared to CAR T cells targeting region I." (PMID 33588928, 2021). "High levels of soluble mesothelin predict a poor prognosis, perhaps as a marker of tumour load." (PMID 34226685, 2021).